RECQL (RecQ like helicase)
Diseases named in the same sentence as RECQL in open-access papers (continued):
Sharing a sentence is not in itself a finding about the gene and the disease.
breast cancer (continued). "Moreover, the loss of function in DNA helicase genes including RECQL, BLM, WRN, RECQL5, and BRIP1 are also known to be highly correlated with the carcinogenesis of breast cancer and the BRCAness phenotype in breast cancer." (PMID 35855837, 2022). "In Poland, 20 founder mutations in BRCA1, BRCA2, CHEK2, PALB2, NBN, RECQL are responsible for the majority of hereditary breast cancer cases in women, but the utility this genes panel has not been tested in men." (PMID 34461861, 2021). "Apart from two studies conducted in an East Asian population from China, data on the contribution of pathogenic RECQL variants to early-onset and/or familial breast cancer patients from other Asian regions are lacking." (PMID 33342430, 2020). "Mutations in RECQL have not been linked to a syndrome, but loss of RECQL has been associated with breast cancer predisposition, perhaps by inducing replication-associated DNA DSBs." (PMID 32820027, 2020). "Much of this work does not support the association between increased breast cancer risk and loss of function RECQL mutations." (PMID 30610487, 2019). "By extending their findings, we could demonstrate that RECQL expression was strongly associated with worse DRFS and DSS in Chinese women with breast cancer." (PMID 29914420, 2018). "Although several studies have reported that RECQL mutations were correlated with the susceptibility to breast cancer, the effect on prognosis in breast cancer was not yet clarified." (PMID 29914420, 2018). "In the second cohort of 322 breast cancer patients, low expression of RECQL protein was also subject to poor survival in breast cancer, and it was an independent prognosis factor of poor DRFS by multivariate analysis (DRFS: adjusted HR: 2.12, 95% CI: 1.16–3.88, P = 0.015)." (PMID 29914420, 2018). "Therefore, we further screened the RECQL gene in an additional 439 unrelated familial breast cancer patients." (PMID 25945795, 2015). "We further screened the RECQL gene in an additional 439 unrelated familial breast cancer patients." (PMID 25945795, 2015). "Moreover, patients with RECQL mutations were more likely to have a family history of breast cancer than those without." (PMID 38439896, 2024). "In addition, compared to non-mutated patients, patients with RECQL mutations were more likely to have a family history of other tumors, particularly breast cancer (52.00% vs. 37.31%; 38.00% vs. 20.27%)." (PMID 38439896, 2024). "While RECQL has not been previously associated with a defined human chromosomal instability disorder, monoallelic germline mutations have been associated with a moderately increased risk of breast cancer." (PMID 35025765, 2022). "However, BARD1 and RECQL were only associated with breast cancer, without increased risk for any other diseases." (PMID 33959510, 2021). "In the present study, we determined the contribution of pathogenic RECQL variants to hereditary breast cancer in 302 early-onset and familial BRCA1 and BRCA2 negative patients with ER positive and/or PR positive breast cancer in a South Asian population from Pakistan." (PMID 33342430, 2020). "However, the frequencies of these twenty mutant alleles of BRCA1/2, CHEK2, PALB2, NBN, and RECQL have not been measured in a large series of early-onset breast cancer patients from Poland." (PMID 32824581, 2020). "However, prior to the potential association with breast cancer susceptibility, mutations in RECQL had not previously been reported in any human genetic disorders." (PMID 30610487, 2019). "The expression level of RECQL may be a potential prognosis factor for breast cancer." (PMID 29914420, 2018). "The underlying mechanism of RECQL expression affect breast cancer prognosis was not yet clear." (PMID 29914420, 2018).
breast cancer (continued). "Here, by sequencing the entire exomes of nine early-onset familial breast cancer patients without BRCA1/2 mutations (diagnosed with breast cancer at or before the age of 35) we found that two index cases carried a potentially deleterious mutation in the RECQL gene (RecQ helicase-like; chr12p12)." (PMID 25945795, 2015). "However, RECQL gene mutations among Chinese women with breast cancer have not been evaluated." (PMID 38439896, 2024). "A correlation has been observed between poor breast cancer prognosis and lower levels of RECQL (also known as RECQ1 and RECQL1) mRNA or RECQL protein expression." (PMID 35712517, 2022). "Of all patients, 58 had RECQL gene mutations, 50 had a variant of uncertain significance (VUS), seven had benign non-pathogenic breast cancer, and one had a probable pathogenic type." (PMID 38439896, 2024). "They observed that a higher expression of RECQL mRNA was correlated with shorter relapse-free survival (RFS) (HR: 1.28, p-value <0.001, n= 3955) and post-progression survival (PPS) (HR: 1.32, p-value: 0.027, n= 414) in all breast cancers." (PMID 35712517, 2022). "Other PVs were identified in genes that have a less clear association with breast cancer such as: BRIP1, NBN, RAD50 and RECQL, but none of these showed significant associations." (PMID 34439310, 2021). "We don’t observe significant differences in the allele frequencies between different regions of Poland, i.e., for BRCA1, PALB2, CHEK2, NBN, RECQL, and also for the GEN1 founder p.Lys645Cysfs*29 variant, neither in breast cancer cases nor in controls (for GEN1 data)." (PMID 40649769, 2025). "Taken together, these studies show frequencies of RECQL loss of function variants of 0–2.6% in patients with high-risk familial breast cancer who have previously tested negative for mutations in BRCA1/BRCA2 and other hereditary breast cancer genes." (PMID 30610487, 2019). "When the expression of RECQL is insufficient, RECQL maybe not play its normal role in maintaining genomic stability, which makes the tumor cells more likely to undergo malignant transformation, and ultimately lead to poor prognosis of breast cancer." (PMID 29914420, 2018).
Werner syndrome (20 papers, 2008 to 2024). "Mutation in Werner (WRN) RECQL helicase is associated with premature aging syndrome (Werner syndrome, WS) and predisposition to multiple cancers." (PMID 35582959, 2022). "Moreover, the low bone mass associated diseases Werner’s syndrome and Hutchinson Gilford Progeria syndrome are caused respectively by loss of the DNA repair enzyme WRN RecQ like helicase (Wrn) or the nuclear matrix protein Lmna." (PMID 37378024, 2023). "RECQL encodes a protein that is part of a family of five RECQ helicases, including at least three implicated in cancer-prone syndromes, such as Bloom Syndrome, Werner Syndrome, and Rothmund-Thomson Syndrome." (PMID 32957588, 2020). "In addition, genes that cause progeria were also included, specifically UBE2I for Progeria and FEN1 and RECQL for Werner syndrome, suggesting a role for the common JAGs to hamper the premature aging." (PMID 29449671, 2018). "However, it has been recently shown in Xenopus laevis, that the WRN (Werner's syndrome) RecQ-like helicase also acts at the initiation step of homologous recombination in the unwinding of broken DNA ends." (PMID 18294364, 2008). "There are five members of RecQ, which are RECQL (also called RECQL1), BLM (Bloom’s syndrome gene), WRN (Werner’s syndrome gene), RECQL4, and RECQL5 with unique biochemical functions." (PMID 35267530, 2022). "Werner syndrome (WS; MIM #277700), sometimes termed progeria of adulthood, is a rare autosomal recessive disorder caused by a defective helicase due to homozygous or compound heterozygous mutations in the WS RecQ-like Helicase gene (WRN; MIM #604611)." (PMID 30023403, 2018). "In addition, Werner Syndrome RecQ Like Helicase (WRN) has a key part in recombination, transcription, repair, and DNA replication, as well as telomere maintenance, suggesting that the prominent inducer for Werner syndrome pathogenesis associated with genomic instability." (PMID 28030852, 2017). "In human cells, the RecQ helicase family comprises five DNA helicases: RECQL1 (also known as RECQL or RECQ1), Bloom syndrome (BLM), Werner syndrome (WRN), Rothmund–Thomson syndrome (RTS; also known as RECQL4) and RECQL5." (PMID 25620975, 2014).
Bloom syndrome (18 papers, 2013 to 2024). Bloom syndrome (BSyn) is a rare chromosomal breakage syndrome characterized by a marked genetic instability associated with pre- and postnatal growth retardation, facial sun-sensitive telangiectatic erythema, increased susceptibility to infections, and predisposition to cancer. "Mutations in BLM, a RecQ-like helicase, have been linked to the autosomal recessive cancer-prone disorder Bloom’s syndrome." (PMID 37875822, 2023). "Bloom’s syndrome (BS), an autosomal recessive human disorder caused by mutations of the recQ-like helicase BLM, is associated with several characteristics of nucleolar dysfunction." (PMID 27657136, 2016). "BLM encodes a RECQL-DNA helicase and is involved in the recessive Bloom syndrome, which predisposes to CRC." (PMID 26901136, 2016). "Bloom’s syndrome, an autosomal recessive human disorder caused by mutated recQ-like helicase BLM, presents with growth defects suggestive of underlying defects in rRNA transcription." (PMID 27657136, 2016). "Also, patients with Bloom syndrome (BS, an autosomal recessive genetic disorder) lack or have a mutated BLM-RecQ-like helicase crucial for genome integrity or stability." (PMID 33643304, 2020). "The BLM RecQ-like helicase prevents SCE events, therefore their identification in metaphases is a cytogenetic marker of Bloom syndrome and other syndromes of the chromosomal instability." (PMID 37052241, 2023). "The BLM gene, responsible for Bloom’s syndrome, was cloned in 1995 and found to share sequence similarities with the RECQ family of DNA helicases, including RECQL/RECQ1." (PMID 37626846, 2023).
ovarian carcinoma (16 papers, 2013 to 2025). A malignant neoplasm originating from the surface ovarian epithelium. "In this study, we have characterised the spectrum of FANCM and RECQL mutations in women affected with breast or ovarian cancer from South-West Poland and West Ukraine." (PMID 29351780, 2018). "Similarly, RECQL, a gene associated with breast/ovarian cancer, was found in a patient diagnosed with rectal cancer at 26 years old, underscoring the need to explore co-occurring cancer syndromes in this population." (PMID 40627234, 2025). "The results showed that high expression of XPC and RECQL and low expression of DMC1 were associated with poor prognosis in ovarian cancer patients." (PMID 31572446, 2019). "In the scope of the German Consortium for Hereditary Breast and Ovarian Cancer, other candidate genes (e.g., NBN, FANCM, XRCC2, and RECQL) are currently co-analyzed for research purposes and their significance in contributing to breast and ovarian cancer is under investigation." (PMID 34680878, 2021). "RECQL has been found to be overexpressed in many other tumors and plays a critical role in malignant progression and PARPi resistance and may serve as a potential prognostic or predictive factor for ovarian cancer." (PMID 31572446, 2019). "Overexpression of BLM RecQ like helicase (BLM) is able to induce DNA damage and increase sensitivity to platinum agents in triple-negative breast cancer and ovarian cancer." (PMID 33995018, 2021). "On the other hand, low expression of DMC1 has been reported as a poor prognostic marker of ovarian cancer, together with high expression of XPC and RECQL." (PMID 33202377, 2020).
multiple myeloma (8 papers, 2017 to 2023). "RECQL helicase has also been found to protect multiple myeloma cells from melphalan and bortezomib cytotoxicity." (PMID 36998465, 2023). "Another study showed that RECQL-overexpression in myeloma cells were resistant to melphalan and bortezomib, whereas silencing RECQL expression can make cells more sensitive to these two drugs." (PMID 29914420, 2018).
glioma (5 papers, 2011 to 2025). A benign or malignant brain and spinal cord tumor that arises from glial cells (astrocytes, oligodendrocytes, ependymal cells). "PARK7 was significantly increased in both GBM and GIV sample groups, relative to controls and RECQL was a top-50 DE plasma-EV protein, with high levels distinguishing GIV from GIII gliomas (10.7-fold, adj." (PMID 32635403, 2020).
pancreatic cancer (5 papers, 2007 to 2023). "Particularly, polymorphic variants in RECQL was found to be related to the overall survival rate of pancreatic cancer patients treated with gemcitabine." (PMID 36998465, 2023). "Lower OS is linked to increased expression of RECQL, BLM, and WRN in pancreatic cancer." (PMID 37626815, 2023).
lung carcinoma (4 papers, 2011 to 2020). "In this study, we described a new frameshift deletion c.363_364del in the RECQL gene in a male with infiltrating ductal breast and prostatic cancer at 59 and 70 years of age, respectively, with a positive family history for breast and lung cancer." (PMID 32957588, 2020).
Rothmund-Thomson syndrome (4 papers, 2013 to 2020). "Although no hereditary disease has been linked with the RECQL gene to date, mutations in three of five RecQ genes, BLM, WRN and RECQ4, lead to Bloom, Werner, and Rothmund-Thomson syndromes, respectively, and are associated with cancer predisposition and/or premature aging." (PMID 25945795, 2015).
breast tumors (3 papers, 2017 to 2022). "Second, mutation analysis was restricted to patients with ER and/or PR positive breast tumors, in whom a predominance of pathogenic RECQL mutations has been reported." (PMID 33342430, 2020).
familial breast cancer (2 papers, 2015 to 2019). "Mutations in RECQL gene identified in the 448 BRCA1/2-negative familial breast cancer patients." (PMID 25945795, 2015).
acute leukemia (1 paper, 2023). A clonal (malignant) hematopoietic disorder with an acute onset, affecting the bone marrow and the peripheral blood. "In this study, we performed WES sequencing in a familial leukemia case, and for the first time to our knowledge, found a germline RECQL mutation potentially involved in hereditary predisposition to acute leukemia." (PMID 36998465, 2023). "Considering the driving role of these two different fusion genes in the occurrences and development of corresponding leukemias, it can be inferred that this RECQL gene variant (rs146924988) is potentially associated with the generation of acute leukemia." (PMID 36998465, 2023). "Comprehensive genetic testing showed that a single nucleotide variant (SNV) in RECQL, rs146924988, was potentially involved in this familial case with acute leukemia." (PMID 36998465, 2023). "Therefore, the significance of RECQL mutation in the treatment of acute leukemia needs to be evaluated in future studies." (PMID 36998465, 2023).
chromosomal instability syndrome (1 paper, 2022). "In summary, we demonstrate that mutations in RECQL are the underlying cause of an inherited chromosomal instability syndrome that shares some clinical and cellular phenotypic similarities with WS." (PMID 35025765, 2022). "However, even with the rapid advances in whole-exome/genome sequencing technology, mutations of the 2 remaining RecQ helicase genes (RECQL and RECQL5) have yet to be linked to an inherited chromosomal instability syndrome." (PMID 35025765, 2022).
Hereditary breast cancer (1 paper, 2023). "Prior to this report, the RECQL germline mutation has been found to be associated with hereditary breast cancer and hereditary ovarian cancer syndrome, but its role in hematological malignancies has not been reported." (PMID 36998465, 2023).
hereditary cancer (1 paper, 2022). Malignant neoplasms occurring in families at a rate greater than that expected by chance and caused by germline mutations in a specific gene.
IgA nephropathy (1 paper, 2026). "Transcriptomic-wide MR identified candidate genes across GN subtypes: RECQL, BRSK2, and MGP in acute GN; AFM, CFHR5, and EPHB2 in chronic GN; IL6R, MBL2, and PRSS3 in IgA nephropathy; and TIMP4, HCK, and PEAR1 in membranous nephropathy." (PMID 41990104, 2026).
leukemia (1 paper, 2023). A malignant (clonal) hematologic disorder, involving hematopoietic stem cells and characterized by the presence of primitive or atypical myeloid or lymphoid cells in the bone marrow and the blood. "This gene variant potentially led to a relative lack of RECQL protein, disordered DNA repair and chromatin rearrangement, which may mediate the occurrence of fusion genes, as driving factors for leukemia." (PMID 36998465, 2023). "Further Sanger sequencing showed no such mutation of RECQL in the healthy child of the proband, which indicated that rs146924988 might play a role in this case of familial leukemia." (PMID 36998465, 2023).
neuroblastoma (1 paper, 2020). Neuroblastoma (NB) is the most common solid, extracranial childhood tumor. "RECQL overexpression is reported in GBM and RECQL has also been identified in cell-derived memetic nanovesicles and exosomes derived from neuroblastoma." (PMID 32635403, 2020).